OXTR (oxytocin receptor)
Diseases named in the same sentence as OXTR in open-access papers (continued):
Sharing a sentence is not in itself a finding about the gene and the disease.
Anxiety (continued). "While these studies support OXTR genotypes conferring greater vulnerability for psychopathology in adverse environments, it is unclear whether genetic variants in OXTR moderate alcohol withdrawal-related anxiety and depression." (PMID 37520225, 2023). "However, the interaction between alcohol withdrawal and the OXTR gene polymorphism on anxiety and depression remains unclear." (PMID 37520225, 2023). "Therefore, SNP rs53576 in the OXTR gene emerges as a genetic risk-factor for trait anxiety which may be especially important for males." (PMID 32957930, 2020). "Hence, future studies could include measurements of epigenetic modulations of the OXTR gene, mRNA and OXTR expression, or sensitivity to oxytocin, as well as more elaborate (endo)phenotypes and underlying characteristics of depression and anxiety." (PMID 28353027, 2017). "Hence, the effects of early life stress on depression and anxiety may depend on variants of the OXTR gene, indicating that certain OXTR SNPs confer differential susceptibility to stressful early life environments." (PMID 28353027, 2017). "Building upon the published cumulative genetic risk score, we calculated an extended OXTR genetic risk score by adding in the risk information from rs968389, an independent SNP locus which we found to be implicated in maternal oxytocin response and maternal separation anxiety from the infant." (PMID 27872764, 2016). "There has been particular interest in the oxytocin receptor (OXTR) gene as certain single nucleotide polymorphisms (SNPs) have been linked to empathy, trust, and maternal behavior and interact with exposure to life events to increase the risk of anxiety and depression in females." (PMID 24523928, 2014). "Most importantly, the deletion of OXTR in CeL astrocytes from sham-operated mice was sufficient to trigger an elevated level of basal anxiety compared to sham-operated mice expressing OXTR in astrocytes." (PMID 40141416, 2025). "Moreover, recent studies have highlighted that OXTR polymorphisms interact with early environmental factors such as parenting experiences to shape social and emotional outcomes, underscoring the importance of gene-environment interplay in anxiety-related traits." (PMID 41356682, 2025). "Previous studies have often examined these facets—peripheral OT levels, OXTR genetics, and clinical anxiety—in isolation." (PMID 41356682, 2025). "In support, astrocytic OXTR signalling in the rat central amygdala has recently been shown to be essential for OXT-induced reduction in pain-related anxiety." (PMID 39702695, 2025). "While the involvement of neuronal OXTR-mediated signalling in anxiety-related and multiple other behaviors has been extensively studied the contribution of astrocytic OXT signaling has received limited attention until now." (PMID 39702695, 2025). "For instance, OXTR in the central amygdala is involved in emotion discrimination, the fear response, and anti-anxiety." (PMID 39277552, 2025). "Fourteen consecutive days of defeat conditioning leads to anxiety-like behaviors and downregulation of OXTR in the ACC of Mandarin voles." (PMID 39081850, 2024). "OXT microinjection in CeA promoted social preference and reduced the anxiety levels, whereas CeA infusion with OXTR-antagonist dose-dependently reduced sociality and increased anxiety." (PMID 38017588, 2023). "OXTR variations were implicated in ASD, ADHD, BPD, aggression, anxiety and depression, PTSD, schizophrenia, alterations of brain volumes, and other psychiatric disorders." (PMID 37153633, 2023). "Activation of the PVN–ACC circuit alleviates pain and anxiety-like behavior in a mouse model of neurological injury, and these effects are blocked by OXTR antagonism." (PMID 37445607, 2023). "A greater DNA methylation level in the OXTR gene was shown in subjects with anxiety and depression who carried the rs53576 AA genotype in the OXTR gene, in comparison with controls." (PMID 37153633, 2023).
Anxiety (continued). "The interaction of alcohol dependence level and OXTR rs2254298 accounted for a significant portion of the variance in anxiety symptoms (β = 0.16, p < 0.05)." (PMID 37520225, 2023). "Our study investigated the interaction between OXTR rs2254298 and the current alcohol withdrawal environment on anxiety symptoms, providing evidence for the weak differential susceptibility model." (PMID 37520225, 2023). "Traditional hierarchical regression analysis was conducted to identify the interaction between OXTR rs2254298 and alcohol dependence level for anxiety symptoms." (PMID 37520225, 2023). "The partial correlation value of 0.13 and half correlation value of 0.12 for the modulating effect of the OXTR SNP on anxiety that we reported can be considered small but meaningful effect sizes, with conversion calculations giving R2 of 0.017 and 0.014." (PMID 37520225, 2023). "First, a multiple linear regression was used to set the alcohol dependence level, OXTR.rs2254298, interaction terms as the primary predictor variable, and depression or anxiety as an outcome; age and educational years were covariates." (PMID 37520225, 2023). "Previous studies indicated that people with different genotypes of OXTR rs2254298 were reported to suffer from more significant depressive or heightened anxiety symptoms when experiencing early adversity." (PMID 37520225, 2023). "To clarify if oxytocin receptor mediates anti‐anxiety effect in activating PVN oxytocin neurons, we injected rAAV‐Oxytocin‐Cre and DIO‐hM3Dq‐mCherry into both sides of PVN while implanted the cannula into CeA." (PMID 37248645, 2023). "High levels of OXTR mRNA expression were observed in the amygdala, an area of the brain that has a critical role in mediating anxiety and stress-responsiveness." (PMID 36077337, 2022). "A similar study investigating postmenopausal women with anxiety and depression, found oxytocin receptor methylation to be increased in a subgroup of rs53576 AA carriers when compared to healthy age-matched female controls." (PMID 35672748, 2022). "Findings in psychiatric disorders in general point to an increased methylation status of the OXTR promoter region with decreased peripheral gene expression in individuals afflicted with depression, anxiety or situations of increased stress." (PMID 35672748, 2022). "Oxytocin administration in male prairie voles has also been shown to increase partner preference and to decrease anxiety‐related behaviour, whereas the administration of an oxytocin receptor antagonist decreases parental behaviour in adulthood." (PMID 34713517, 2021). "Activation of the oxytocin receptor (OTR) in the medial prefrontal cortex reduces anxiety levels in male mice and increases social motivation in females." (PMID 34045941, 2021). "Maternal diabetes-induced OXTR suppression contributes to anxiety-like behavior, while it has less of an effect on ALB; moreover, prenatal OXTR deficiency potentiates maternal diabetes-mediated social deficits." (PMID 33633538, 2021). "Childhood abuse has been reported to induce anxiety and depression in a manner dependent on DNA methylation of the oxytocin receptor gene." (PMID 34713517, 2021). "With regards to the Italian sample, the first step considered only the OXTR variation in explaining the levels of anxiety and avoidance." (PMID 33919740, 2021). "Early postnatal administration of an oxytocin receptor agonist has been shown to attenuate microglial inflammation and to normalize myelination, brain connectivity, and cognitive and anxiety-related behaviors in an early life stress model." (PMID 35008574, 2021). "Some studies have reported a potential or direct relationship between of the OXT/OXTR signaling system and social recognition, object recognition, object location memory, anxiety behavior, fear-related behavior, and depressive behavior." (PMID 32719656, 2020).
Anxiety (continued). "OT mediated by OXTR has been shown to improve social symptoms in autism, reduce anxiety, and induce long-term potentiation in the rodent brain through CREB phosphorylation via activation of c-Raf/MEK/ERK/CREB signaling." (PMID 33134294, 2020). "Oxytocin receptor (OXTR), a key regulator of stress and anxiety, is also affected by gonadal hormones and psychosocial risk factors." (PMID 33015076, 2020). "Social bonding is impaired, while the prevalence of anxiety is increased in individuals with ASD suggesting less sensitivity to oxytocin caused by an abnormality in oxytocin receptor (OXTR) density during an early life period." (PMID 33122985, 2020). "Polymorphisms of the oxytocin receptor gene (OXTR) in healthy populations have been related to differences in personality characteristics, including neuroticism, self-esteem, anxiety, and autistic traits." (PMID 30542304, 2018). "Taken together, these findings suggested that OXT acted specifically on the CeA via OXTR to modulate depression and anxiety-related behaviors." (PMID 30158853, 2018). "In the current study, we found that OXTR mRNA in the CeA is down-regulated after long-term isolation and OXT rescues the isolation-induced depression- and anxiety-related behaviors by acting on OXTR in the CeA." (PMID 30158853, 2018). "Previous studies indicate that OXTR null mice display motor activity and anxiety behavior similar to normal mice, consistent with our results." (PMID 29945877, 2018). "The oxytocin receptor (OXTR) is another gene that appears to be a factor in the etiology of anxiety and depression." (PMID 26175754, 2015). "The OXTR gene showed a higher methylation in the anxiety/depression group, but only when subjects were stratified by SNV rs53576 genotypes." (PMID 26175754, 2015). "For OXTR, a greater DNA methylation was observed in subjects with anxiety/depression, but only for those carrying the AA genotype of the OXTR rs53576 SNV, more particularly at one out of the seven CpGs studied (7.01 ± 0.94 vs. 4.44 ± 1.11; p= 0.0063)." (PMID 26175754, 2015). "In animals, patterns of OXTR expression in the central nervous system have long suggested a contribution of OXTR to the regulation of anxiety and to defensive maternal behavior." (PMID 22846218, 2012). "Additionally, hyperglycemia induced persistent oxidative stress, inhibited oxytocin receptor expression, and potentiated maternal diabetes-mediated anxiety-like behavior." (PMID 41590515, 2026). "Similarly, a three-day social defeat conditioning in prairie voles induces anxiety-like behaviors, social avoidance, and progressive downregulation of OXTR in the NAc, ACC, and BLA over an eight-week period." (PMID 39081850, 2024). "For the interaction for anxiety, the partial correlation value of 0.13 and the semi-partial correlation value of 0.12 indicated that 1.4–1.7% of the variance in anxiety could be explained by alcohol dependence level × OXTR rs2254298 interaction." (PMID 37520225, 2023). "The level of alcohol dependence correlates with anxiety risk in AUD patients, which may vary by OXTR genotypes." (PMID 37520225, 2023). "The OXT/OXTR system mediated anxiety-like behavior and response to stress in mammals." (PMID 37153633, 2023). "As alcohol withdrawal represents a profound physiological stressor, OXTR genotypes that worsen oxytocin’s regulation of stress reactivity could intensify withdrawal-related anxiety, reflecting the immediate effects of the three-week acute withdrawal period." (PMID 37520225, 2023). "As reviewed above, the OXT/OXTR system regulates social cognition, social behaviors, emotions, and autonomic functions, including social memory, maternal behavior, attachment, mating, sexual behavior, depression, anxiety, aggression, and others." (PMID 37153633, 2023).
Anxiety (continued). "Furthermore, epigenetic down-modulation of OXTR was related to high levels of separation anxiety and arousal in response to social separation in rhesus macaques experiencing maternal deprivation stress during the neonatal period." (PMID 37153633, 2023). "OXT and the OXTR are involved in regulation of anxiety, stress, and reward-related behaviors." (PMID 36077337, 2022). "Since the anxiolytic effect of the OXT is mediated via phosphorylation of ERK1/2, we hypothesize that the attenuated phosphorylation level in OXTR A218T cells accounts, to some extent, for comorbid anxiety found in some cases of ASD." (PMID 34980886, 2022). "More recent preclinical findings in female rodents suggest that chronic social defeat stress might increase the levels of anxiety and depression via a reduction in oxytocin projections and the oxytocin receptor level in the nucleus accumbens." (PMID 35672748, 2022). "In addition, postnatal infusion of OXTR reversed maternal diabetes-mediated anxiety-like behavior, while it had little effect on ALB; on the other hand, postnatal infusion of ERβ completely reversed maternal diabetes-mediated social deficits." (PMID 33633538, 2021). "Both affiliative tactile stimuli and early‐life adverse stimuli in the neonatal period acutely activate the oxytocin–oxytocin receptor system in the brain but modulate social behaviour and anxiety‐related behaviour apparently in an opposite direction in adulthood." (PMID 34713517, 2021). "Polymorphisms in the oxytocin receptor (OXTR) gene are related to individual differences in negative emotions, such as depressive symptoms and anxiety." (PMID 35222513, 2021). "Our results indicate that increasing postnatal expression of OXTR in amygdala reverses maternal diabetes-induced anxiety-like behavior but has little effect on ALB, while expression of ERβ completely reverses maternal-diabetes-induced social deficits in offspring." (PMID 33633538, 2021). "OXTR knockout mice displayed an effect mimicking that of the maternal diabetes group as compared to the control (CTL/OXTR–/–) group, and interestingly, it further potentiated the maternal diabetes-mediated anxiety-like behavior in diabetic (STZ/OXTR–/–) group compared to STZ/WT group." (PMID 33633538, 2021). "At Step 6, the hypothesized interaction between OXTR and paternal bonding dimensions on anxiety was tested (f2 = 0.39, power = 0.99)." (PMID 33919740, 2021). "In addition, SNP rs53576 in the oxytocin receptor gene (OXTR) associates with depressive symptomatology, stress-responsive activity and increased anxiety." (PMID 32957930, 2020). "Because most projecting neurons in the hippocampus are glutamatergic, we assumed that anxiety might be suppressed via the activation of inhibitory neurons, including the OXTR+ neurons in the LS." (PMID 33335150, 2020). "Recently, it was reported that maternal deprivation in rhesus macaque caused alterations of H3K4me3 level binding at genes using a ChIP-sequencing assay and that the most robust gene is OXTR, which was correlated with the phenotypes of separation anxiety and arousal observed." (PMID 33134294, 2020). "We indicated the suppressive function of activation of OXTR+ neurons in the LS on anxiety behavior." (PMID 33335150, 2020). "Notably, out of the 20,737 gene expression brain maps that we compiled, the OXTR expression map was among the top 0.5% of strongest relationships with the “sexual”, “motivation”, “incentive”, and “anxiety”, cognitive state maps." (PMID 30737392, 2019). "In sum, while the OXTR gene has been found to play a role in social processes and underlying characteristics of both anxiety and depression, there is little evidence for a role of the OXTR in the etiology of clinical expressions of anxiety and depression." (PMID 28353027, 2017). "This reinforces the finding of the absence of interplay between CM and the OXTR gene variants in depression and anxiety." (PMID 28353027, 2017).
Anxiety (continued). "In contrast, quite a few candidate gene studies, often in non-clinical samples, have shown main effects of OXTR genes on underlying characteristics of depression and anxiety, which we were not able to replicate." (PMID 28353027, 2017). "The OXTR gene has been less studied in relation to anxiety/depression." (PMID 26175754, 2015). "This potent OTR antagonist has been used to determine the involvement of the oxytocin receptor in various behaviours, namely pain modulation and anxiety, and has previously been used by our group to determine oxytocin mechanisms in acute METH reward and chronic METH exposure." (PMID 26284529, 2015). "The oxytocin receptor OTR is found in several regions of the brain, including areas involved in the pathophysiology of neurodegenerative diseases such as Alzheimer’s disease, Parkinson’s disease, depression, anxiety, schizophrenia, autism, and attention deficit hyperactivity disorder." (PMID 39201299, 2024). "Hierarchical multiple regression revealed that the OXTR rs2254298 gene polymorphism was not directly associated with anxiety symptoms during withdrawal; however, the interaction between OXTR rs2254298 and alcohol dependence level had a significant effect on anxiety symptoms." (PMID 37520225, 2023). "Thus, higher OXTR methylation and less secure attachment styles might be how OXTR rs2254298 regulates alcohol dependence and anxiety during alcohol withdrawal." (PMID 37520225, 2023). "Similarly, chronic high-dose i.c.v OXT administration (over 14 days) produced an anxiety-like behavioral phenotype and reduced the expression of OXTR levels, whereas chronic low-dose OXT prevented hyper anxiety and reduced ACTH sensitivity and adrenal hypertrophy." (PMID 38017588, 2023). "The oxytocin receptor is expressed in approximately half of the serotoninergic neurons in the raphe nucleus, and local injection of oxytocin into the median raphe decreases anxiety-related behaviors by facilitation of serotonin release, possibly via the serotonin 2A/2C receptor." (PMID 35008574, 2021). "However, deficiency of the oxytocin receptor in serotoninergic neurons in the raphe nucleus has been shown to have no significant influence on anxiety-related behavior, but to enhance aggression only in male mice." (PMID 35008574, 2021). "In dogs, OXTR polymorphisms have been widely linked to human-directed social behaviour, greeting behaviour, proximity seeking and friendliness but so far not to NS or anxiety." (PMID 30655508, 2019). "In contrast, OXTR deficiency did not induce anxiety-like behavior or alter motor activity in mice." (PMID 29945877, 2018). "For assessment of OXT-induced anxiolysis following astrocytic Gem or OXTR knockdown, rats received bilateral OXT infusions 21 d after virus infusions and 10 min prior to assessment of anxiety-related behavior in the EPM and LDB." (PMID 39702695, 2025). "Low OXTR and low BDNF can manifest in social withdrawal, poor attachment, and heightened anxiety since the protective effects of social interaction and neural plasticity for adaptation are reduced." (PMID 41514907, 2025). "Sexual dimorphism in OXT-induced anxiety has been described before and appears to be rooted in differential CRF signaling from OXTR-expressing interneurons in the prefrontal cortex." (PMID 34035479, 2023). "It has been reported that the OXT/OXTR signaling pathway plays a role in regulation of a variety of social behaviors as well as ASD etiology and is involved with anxiety-like behaviors." (PMID 35370982, 2022). "In relation to functional relevance, both the OXTR and 5-HT2CR are expressed in dorsal raphe neurons with their interactions leading to diminished anxiety." (PMID 36618821, 2022). "OXT, in conjunction with oxytocin receptor (OXTR), has been reported to play an important role in regulation of social recognition and anxiety-like behaviors as well as many other kinds of pathophysiological processes." (PMID 35370982, 2022).